EDNRA (endothelin receptor type A)
Description:
Receptor for endothelin-1. Mediates its action by association with G proteins that activate a phosphatidylinositol-calcium second messenger system. The rank order of binding affinities for ET-A is: ET1 > ET2 >> ET3.
Synonyms: ET-A; ETA-R; hET-AR; ETA; ETRA; ETAR; MFDA
Tractability: Small molecule: an approved drug acts on it; a structure with a bound ligand is known; a high-quality ligand is known; it belongs to a druggable protein family. Antibody: its Gene Ontology location is reachable by antibodies, with high confidence; UniProt places it where antibodies can reach, with medium confidence; UniProt predicts a signal peptide or a membrane-spanning region. PROTAC: a small molecule that binds it is known. Other modalities: a drug acting on it is in phase 2 or 3 trials.
Target class: Family A G protein-coupled receptor; Short peptide receptor (family A GPCR); Membrane receptor; Peptide receptor (family A GPCR); Endothelin receptor
Chemical probes: A-216546 (high quality), BMS-182874 (high quality), CI 1020 (high quality), PD082538
Safety:
Unwanted effects reported when the protein is acted on. In parentheses: how it was acted on, where the effect was seen, and who reports it.
aldosterone secretion (Urban et al. (2012): activation, cardiovascular system; Bowes et al. (2012): activation, cardiovascular system, development)
bronchoconstriction (Urban et al. (2012): activation, cardiovascular system; Lynch et al. (2017): activation, acute dosing, nervous system, renal, cardiovascular, gastrointestinal)
increased blood pressure (Bowes et al. (2012): activation, cardiovascular system, development; Lynch et al. (2017): activation, acute dosing, nervous system, renal, cardiovascular, gastrointestinal)
osteoblast proliferation (Urban et al. (2012): activation, cardiovascular system; Bowes et al. (2012): activation, cardiovascular system, development)
teratogenicity (Urban et al. (2012): inhibition, developmental toxicity, cardiovascular system; Bowes et al. (2012): inhibition, developmental toxicity, cardiovascular system, development)
abnormal face (inhibition, developmental toxicity; nervous system, renal, cardiovascular, gastrointestinal; source: Lynch et al. (2017))
cardiac anomaly (inhibition, developmental toxicity; nervous system, renal, cardiovascular, gastrointestinal; source: Lynch et al. (2017))
chromosome 22 deletions (inhibition, developmental toxicity; nervous system, renal, cardiovascular, gastrointestinal; source: Lynch et al. (2017))
cleft palate (inhibition, developmental toxicity; nervous system, renal, cardiovascular, gastrointestinal; source: Lynch et al. (2017))
decreased blood pressure (inhibition, acute dosing; nervous system, renal, cardiovascular, gastrointestinal; source: Lynch et al. (2017))
decreased gastric emptying (inhibition, acute dosing; nervous system, renal, cardiovascular, gastrointestinal; source: Lynch et al. (2017))
decreased heart rate (activation, acute dosing; nervous system, renal, cardiovascular, gastrointestinal; source: Lynch et al. (2017))
decreased intestinal transit (inhibition, acute dosing; nervous system, renal, cardiovascular, gastrointestinal; source: Lynch et al. (2017))
decreased pain (inhibition, acute dosing; nervous system, renal, cardiovascular, gastrointestinal; source: Lynch et al. (2017))
decreased urine excretion (inhibition, acute dosing; nervous system, renal, cardiovascular, gastrointestinal; source: Lynch et al. (2017))
glomerular and tubulointerstitial structural injury (activation, acute dosing; nervous system, renal, cardiovascular, gastrointestinal; source: Lynch et al. (2017))
increased aldosterone secretion (activation, acute dosing; nervous system, renal, cardiovascular, gastrointestinal; source: Lynch et al. (2017))
increased cardiac contractility (activation, acute dosing; nervous system, renal, cardiovascular, gastrointestinal; source: Lynch et al. (2017))
increased cell proliferation (activation, acute dosing; nervous system, renal, cardiovascular, gastrointestinal; source: Lynch et al. (2017))
increased heart rate (inhibition, acute dosing; nervous system, renal, cardiovascular, gastrointestinal; source: Lynch et al. (2017))
increased pain (activation, acute dosing; nervous system, renal, cardiovascular, gastrointestinal; source: Lynch et al. (2017))
pulmonary left ventricular hypertrophy (activation, acute dosing; nervous system, renal, cardiovascular, gastrointestinal; source: Lynch et al. (2017))
thymic hypoplasia (inhibition, developmental toxicity; nervous system, renal, cardiovascular, gastrointestinal; source: Lynch et al. (2017))
vasoconstriction (activation; cardiovascular system; source: Urban et al. (2012))
Gene: Protein-coding gene on chromosome 4 (147,480,917 to 147,544,954, forward strand). Ensembl gene ENSG00000151617.
Subcellular location: Cell membrane
Subcellular location (Human Protein Atlas): Cytosol; Plasma membrane
Pathways (Reactome):
Signal Transduction: G alpha (q) signalling events; Peptide ligand-binding receptors
Gene Ontology:
Molecular function: protein binding; endothelin receptor activity; phosphatidylinositol-4,5-bisphosphate phospholipase C activity; G protein-coupled receptor activity
Biological process: artery smooth muscle contraction; cAMP/PKA signal transduction; intracellular calcium ion homeostasis; positive regulation of cation channel activity; vasoconstriction; activation of adenylate cyclase activity; cell population proliferation; developmental pigmentation; endothelin receptor signaling pathway; G protein-coupled receptor signaling pathway; phospholipase C-activating G protein-coupled receptor signaling pathway; positive regulation of cytosolic calcium ion concentration; respiratory gaseous exchange by respiratory system; signal transduction; smooth muscle contraction; angiogenesis; aorta development; atrial cardiac muscle tissue development; axon extension; axon guidance; axonogenesis involved in innervation; blood vessel remodeling; branching involved in blood vessel morphogenesis; calcium ion transmembrane transport; canonical Wnt signaling pathway; and 49 more
Cellular component: plasma membrane; membrane
Genetic constraint (gnomAD): Loss-of-function variants: 10 observed, 39.97 expected, observed/expected ratio (o/e) 0.25, 90% interval 0.15 to 0.42. The upper end of that interval is the gene's LOEUF score, 0.42, which puts it in group 1 of 6, group 1 being the genes least tolerant of losing a copy. Missense variants: 290 observed, 544.69 expected, observed/expected ratio (o/e) 0.53, 90% interval 0.48 to 0.59. Synonymous variants: 170 observed, 188.1 expected, observed/expected ratio (o/e) 0.9, 90% interval 0.8 to 1.03.
Homologues: Orthologues: chimpanzee EDNRA (100% identical), macaque EDNRA (99% identical), rabbit EDNRA (96% identical), pig EDNRA (95% identical), dog EDNRA (95% identical), rat Ednra (93% identical), mouse Ednra (92% identical), guinea pig EDNRA (89% identical), tropical clawed frog ednra (70% identical), zebrafish ednraa (64% identical), zebrafish ednrab (59% identical). Paralogues in human: EDNRB (54% identical), GRPR (25% identical), NMBR (23% identical), BRS3 (23% identical), GPR37 (22% identical), GPR37L1 (20% identical), NMUR1 (20% identical), NTSR1 (20% identical), GHSR (19% identical), TRHR (18% identical), MLNR (17% identical), NTSR2 (17% identical), and 3 more.
Diseases named in the same sentence as EDNRA in open-access papers:
EDNRA is named in the same sentence as 220 diseases in open-access papers, as found by Europe PMC text mining. Sharing a sentence is not in itself a finding about the gene and the disease. The quoted sentences say what the papers report.
Hypertension (49 papers, 2008 to 2025). The presence of chronic increased pressure in the systemic arterial system. "SNPs in or near the EDNRA gene have been associated with intracranial aneurysm risk, hypertension and migraines." (PMID 23717390, 2013). "Increased EDNRA expression has shown to play an important role in hypertension and thus progression of vascular proliferation." (PMID 40182431, 2025). "For example, quercetin weakens the hypertension induced by uterine perfusion pressure in pregnant rats by reducing the levels of endothelin 1 (ET-1) and endothelin receptor type A (ET-A)." (PMID 34204038, 2021). "Due to influential role of the endothelin pathway in hypertension development, we also investigated the association between EDN1 and EDNRA gene polymorphisms and ischemic stroke development in patients with and without AH." (PMID 29849817, 2018). "In mammals, two independent endothelin receptors, EDNRA and EDNRB, have been linked to high-altitude pulmonary edemas (Sharma, Singh & Sarkar, 2014), as well as hypertension, cardiac hypertrophy, and coronary artery disease (Schneider, Boesen & Pollock, 2007)." (PMID 29018624, 2017). "For instance, MOL170 was observed to decrease EDNRA (Endothelin-1 receptor) level, while previous clinical research indicated that down-regulation of EDNRA significantly reduced blood pressure in hypertension patients." (PMID 26813334, 2016). "Endothelin receptor type A plays an important role in hypertension, vascular remodeling, cardiac hypertrophy and coronary artery disease and is found on pulmonary vascular smooth muscle cells and adventitial fibroblasts." (PMID 24465776, 2014). "Candidates EDNRA, EDN1 and EDNRB function together in a regulatory pathway with endothelin-converting enzyme ECE1, which has been implicated in essential hypertension." (PMID 20886000, 2010). "ET-1, a vasoactive peptide of 21-amino acids, is known as one of the most potential vasoconstrictors, which plays a critical role in the development of hypertension by acting on endothelin receptor type A (ETAR), type B1 (ETB1R), and type B2 (ETB2R) coupled with G proteins." (PMID 35530510, 2022). "Take the most confident prediction as an example, target protein ‘Endothelin-1 receptor’ (EDNRA) for ‘Bosentan’, and the disease gene ‘KCNMB1’ (Kca) for ‘Hypertension, Diastolic, Resistance To’ belong to the same pathway ‘Arachidonic Acid metabolism’." (PMID 24244318, 2013). "Moreover, caveolae, which are lipid raft invaginations in the plasma membrane, mediate hypertension-induced VSMC modeling via endothelial nitric oxide synthase (eNOS) and endothelin receptor type A (ETA)." (PMID 33265898, 2020).
pulmonary arterial hypertension (47 papers, 2011 to 2026). Pulmonary arterial hypertension (PAH) is a group of diseases characterized by mean pulmonary artery pressure >20 mmHg and elevated pulmonary arterial resistance leading to right heart failure. "The locus is strongly linked to the gene encoding endothelin receptor type A (EDNRA), the target of several approved small molecule drugs for pulmonary artery hypertension and type 2 diabetes indications, suggesting a potential repositioning opportunity for other cardiovascular diseases." (PMID 37749083, 2023). "EDNRA gene encodes for endothelin A receptor, against which several antagonists have been developed for the treatment of pulmonary arterial hypertension or which are in advanced clinical phase development for non-small cell lung cancer and diabetic nephropathy." (PMID 30510157, 2018). "Herein, we used bosentan as the endothelin antagonist, which targets two endothelin receptors, EdnrA and EdnrB, with a similar binding affinity and is clinically used to treat pulmonary arterial hypertension." (PMID 38252153, 2024). "EDNRA encodes the endothelin 1 (EDN1) receptor, a gene involved in the vasoconstriction mechanism, as well as closely related to pulmonary hypertension and HIF activity, which is positively selected in Tibetan." (PMID 35087567, 2021). "The EDNRA gene is also involved in the vasoconstriction mechanism, which is closely related to pulmonary hypertension." (PMID 31212963, 2019). "In the context of dual antagonists, bosentan, a compound that concurrently targets both endothelin receptor type A (ETAR) and ETBR, has been approved for addressing pulmonary hypertension." (PMID 38047990, 2023). "The development of endothelin receptor antagonists (ERAs) such as bosentan, a dual EDNRA and EDNRB receptor antagonist, or BQ123 targeting EDNRA, provided targeted treatments for pulmonary arterial hypertension and cancer." (PMID 30279475, 2018). "Further, several important regulators of systemic/pulmonary hypertension including ADRA1D, ECE1, and EDNRA were upregulated in HAPE." (PMID 24465776, 2014).
ovarian carcinoma (36 papers, 2004 to 2026). A malignant neoplasm originating from the surface ovarian epithelium. "For instance, the endothelin type A receptor, encoded by EDNRA, drives ovarian cancer progression by promoting invadopodia formation through a β-arrestin/PDZ-RhoGEF-mediated mechanism, promotes colorectal cancer progression, and is associated with metastasis in patients with advanced bladder cancer." (PMID 37958718, 2023). "A significant association was seen between EDNRA expression and ovarian cancer stage and grade." (PMID 27600227, 2015). "In line with this, the dual EDNRA/B inhibitor macitentan blocked metastatic progression of ovarian cancer cells, and zibotentan, a specific EDNRA inhibitor showed synergistic effects on apoptosis and inhibition of ovarian cancer cell invasion, when used in combination with EGFR inhibitors." (PMID 35625966, 2022).
breast carcinoma (24 papers, 2004 to 2026). "The TCGA database shows that EDNRA expression in breast cancer patients is associated with immune response and EV biogenesis and secretion." (PMID 35265193, 2022). "So far, overexpressions of EDN1 and EDNRA were already reported as being associated with impaired survival in breast cancer." (PMID 19527488, 2009). "Because EDNRB has been proposed to serve as a negative regulator of endothelin A receptor signaling (EDNRA) 5,9, and considering that EDNRA is a well-known promoter of breast cancer progression 19, EDNRB is expected to be an antagonist to breast cancer." (PMID 32201539, 2020). "Compared to MCF10A, EDNRA expression was elevated in breast cancer cells (MDA‐MB‐231)." (PMID 39601333, 2024). "Thus, the correlation between innate PD-1 resistance signature (IPRES) and EDNRA expression was analyzed, and we observed a significantly positive correlation from TCGA data on breast cancer." (PMID 35265193, 2022). "Furthermore, chemically inhibiting EDNRA inhibits invasion in breast cancer cell lines 19, and ET1 and ET2 both induce breast cancer cell migration in an EDNRA and EDNRB-dependent manner 16,20." (PMID 32201539, 2020). "In addition, blockers of EDNRA resensitised cancer cells to paclitaxel-induced apoptosis, as observed in ovarian, prostatic, cervical and nasopharyngeal cancer cell lines as well as in primary ovarian and breast cancer." (PMID 19527488, 2009). "The drug bosentan, which targets both EDNRA and EDNRB, inhibits tumour growth, vascularisation and bone metastasis in breast cancer." (PMID 19527488, 2009). "Notably, an ET-axis expression pattern similar to that of breast cancer was recently found in cervical cancer; that is, upregulation of EDN1, EDN2, EDNRA and EDNRB expression was accompanied by downregulation of EDN3 expression in cancerous cervix as compared with normal cervical epithelium." (PMID 19527488, 2009).
diabetes (18 papers, 2012 to 2025). "In the present study, the association of DKD with polymorphisms in ET-1 (EDN1) and ETRA (EDNRA) genes was analyzed in patients with type 2 diabetes mellitus (T2DM)." (PMID 26594247, 2015). "EDNRA antagonist treatment prevents mitochondrial oxidative damage in endothelial cells and ameliorates diabetes-induced glomerular injury, suggesting a crosstalk between podocytes and glomerular endothelial cells." (PMID 32733268, 2020). "The aim of this study was to evaluate the association between genetic variants of the ET-1 and ETRA genes (EDN1 and EDNRA) and DKD in patients with type 2 diabetes mellitus (T2DM)." (PMID 26594247, 2015).
systemic sclerosis (13 papers, 2013 to 2025). A chronic disorder, possibly autoimmune, marked by excessive production of collagen which results in hardening and thickening of body tissues. "Agonistic autoantibodies (Aabs) against the angiotensin II receptor type 1 (AT1R) and the endothelin receptor type A (ETAR) have been identified in patients with systemic sclerosis (SSc)." (PMID 24612997, 2014). "Systemic sclerosis IgGs contain a multitude of SSc disease-specific and non-specific antibodies, including agonistic autoantibodies against angiotensin II receptor type 1 and the endothelin receptor type A." (PMID 28228756, 2017).
atherosclerosis (12 papers, 2014 to 2025). A disease characterized by the build-up of fatty material and calcium deposition in the arterial wall resulting in partial or complete occlusion of the arterial lumen. "Our results do not confirm association of ABO rs579459, PPAP2B rs17114036, ADAMTS7 rs3825807, PIK3CG rs17398575, and EDNRA rs1878406 polymorphisms with subclinical atherosclerosis and CV disease in RA patients." (PMID 24795506, 2014). "The proliferation and migration of smooth muscle cells from the media into the intima mediated by EDNRA is significant with atherosclerosis development and progression." (PMID 32214403, 2020). "These six genes are involved in the development of atherosclerosis, including CRP, endothelin receptor type A (EDNRA), PON 1, fibrinogen alpha chain (FGA), fibrinogen beta chain (FGB), and fibrinogen gamma chain (FGG)." (PMID 32214403, 2020). "Signaling of a receptor for endothelin-1, EDNRA, mediates activation and proliferation of VSMC, and its selective inhibitors prevent endothelial dysfunction, structural vascular change in atherosclerosis, and also inhibit cholesterol induced atherosclerosis." (PMID 26488411, 2015).
endothelial dysfunction (11 papers, 2008 to 2025). In vascular diseases, endothelial dysfunction is a systemic pathological state of the endothelium (the inner lining of blood vessels) and can be broadly defined as an imbalance between vasodilating and vasoconstricting substances produced by (or acting on) the endothelium. "Podocyte-derived EDN1 can act on endothelial cells, which mediates oxidative stress and endothelial dysfunction via EDN1 receptor type A (EDNRA) activation, thus promoting podocyte apoptosis." (PMID 32733268, 2020).